MTOR (mechanistic target of rapamycin kinase)
Diseases named in the same sentence as MTOR in open-access papers (continued):
Sharing a sentence is not in itself a finding about the gene and the disease.
cancer (continued). "For this reason, and because of its involvement in signalling cascades that are often disrupted in cancer, mTOR and components of its pathways are attractive anti-cancer drug targets." (PMID 26206669, 2015). "It is established that the PI3K/Akt/mTOR pathway makes a big contribution in many cancers, including colon cancer." (PMID 25965911, 2015). "Our observation that rapamycin, like metformin, also enhances cancer cell sensitivity to vemurafenib emphasizes the importance of mTOR signaling and expands the range of potential adjuvants to include direct and specific mTOR inhibitors." (PMID 26000092, 2015). "Although it specifically suppressed the expression of survivin, we here proved YM155 also targeted the mTOR signaling pathway, which was the principal regulator of cancer cell survival and autophagy." (PMID 26018732, 2015). "Here, we compare the effect of dietary composition and intermittent fasting on cancer growth and mTOR pathway signaling." (PMID 26378060, 2015). "The IR lies upstream of several mitogenic pathways implicated in cancer, including the PI3K/PKB/Akt/mTOR and Ras-MAPK signaling networks." (PMID 25849721, 2015). "The discovery of the connection between TSC and mTORC1 pathway provided the first molecular link between mTOR and cancer." (PMID 26536660, 2015). "The PI3K/AKT/mTOR pathway is commonly activated in human cancers and has a vital role in cell growth, proliferation, survival, apoptosis, and angiogenesis." (PMID 26275051, 2015). "A correlation of MMP9 with mTOR expression in intestinal type cancers was only of weak character and doesn't support mTOR as being the main regulating factor." (PMID 26652716, 2015). "The mTOR pathway is frequently activated in various cancers, which is account for cell growth, proliferation and metastasis." (PMID 25996501, 2015). "Based on these findings, the mTOR pathway is regarded as a promising therapeutic target for some human cancers; consequently, specific inhibitors of mTOR complexes, such as rapamycin analogs (Rapalogs) and mTOR kinase inhibitors, are being actively developed." (PMID 25906254, 2015). "AKT and mTOR function as “master switch” proteins in cancer cells to modulate metabolism, cell cycle, and apoptosis." (PMID 26375441, 2015). "In this review, we summarise the current knowledge of the roles of the PI3K/Akt/mTOR signalling pathway in HPV-induced cancers." (PMID 26022660, 2015). "Because of the central role of mTOR in cancer biology, its inhibitors are targets for the development of anticancer drugs." (PMID 26302180, 2015). "It will be worthy to evaluate if the dysregulation of H3K4 trimethylation depends on Skp2 in other mouse models of cancers, and furthermore the relevance in mTOR signaling pathway." (PMID 25596733, 2015). "AMPK also controls cell growth, proliferation and autophagy through the modulation of mammalian target of rapamycin (mTOR) activity, which is consistently deregulated in cancer cells." (PMID 26656173, 2015). "mTOR inhibitors have become a new and important tool against cancer, for example in renal cell carcinoma." (PMID 26097685, 2015). "Surprisingly, knockdown of mTOR in HD1A cells showed an increased stimulatory effect on cancer cells." (PMID 25807535, 2015). "The CR was seen after 6 cycles of DAT, and the patient has been cancer free for more than 5 years and continues on maintenance therapy with the mTOR inhibitor as a single agent." (PMID 26244164, 2015). "In recent years, the serine/threonine kinase mTOR has become an important and attractive therapeutic target for cancer therapy and numerous studies demonstrated that mTOR kinase negatively regulates autophagy." (PMID 26134510, 2015). "Recent studies suggest that mTOR plays an important role in PI3K/AKT-mediated signaling for cancer stem cell self-renewal and resistance to chemotherapy or radiotherapy." (PMID 25635866, 2015).
cancer (continued). "The inhibitory results of NVP-BEZ235 in CLL correspond with the effectiveness of NVP-BEZ235 treatment in other AKT/mTOR-driven cancer types, as well as with previous data demonstrating suppression of eIF4G activity and 4E-BP1 phosphorylation in AML." (PMID 25999352, 2015). "Initiation of an AMPK-dependent energy stress response, resulting in inhibition of the mammalian target of rapamycin (mTOR) signaling pathway, leads to reduced protein synthesis and proliferation of cancer cells." (PMID 25935404, 2015). "This study demonstrates that YC regulates the AMPK/mTOR signaling pathway and inhibits actin cytoskeleton organization in human lung H1993 cancer cells." (PMID 26656173, 2015). "We demonstrated that mTOR signaling was activated in CD133-positive cancer cells in human primary NPC in a previous study." (PMID 26202311, 2015). "Numerous observations support the importance of mTOR pathway in cancer development, particularly oncogenic activation of mTOR signaling induces processes required for cancer cell proliferation." (PMID 26636543, 2015). "The findings of cancer research studies have indicated that PTEN is an upstream inhibitory mediator of mTOR, which also has been confirmed in the central nervous system (CNS)." (PMID 25889774, 2015). "Given that the AKT and mTOR activations are important for metabolic regulation of cancer cells, we further investigated the metabolic changes conferred by PTEN deficiency in NSCs." (PMID 26632666, 2015). "In the last few years, several mTOR ATP-competitive inhibitors have been reported acting upon mTOR in both complexes and showing a more complete anti-cancer activity in comparison with that of rapamycin and its derivatives." (PMID 25741318, 2015). "A genome-wide analysis has shown that E6 up-regulates many genes at the transcript level associated with cancer hallmarks including cell cycle, migration, PI3K/Akt /mTOR signalling to mediate cellular transformation." (PMID 26022660, 2015). "The purpose of the present study was to investigate the involvement of NQO1 in the activation of AMPK and the suppression of mTOR in cancer cells under oxidative stress (more specifically, OGD)." (PMID 25586669, 2015). "This progress has emphasized PI3K/AKT/mTOR, among others, as a central signaling center of cancer development due to its governing control in cellular growth, survival, and metabolism." (PMID 26056603, 2015). "Metformin alters cancer cell metabolism and it inhibits mitochondrial complex 1 and the mTOR pathway, which is a major regulator of cell metabolism and proliferation." (PMID 26002551, 2015). "There are a number of negative feedback mechanisms that control signaling through the PI3K/Akt/mTOR pathway that need to be considered when designing drug targeting strategies for human cancer." (PMID 26793165, 2015). "Several studies have shown that mTOR inhibitors have radio-sensitizing effects on a number of malignant tumors, such as breast cancer." (PMID 25887043, 2015). "The mTOR inhibitor and some of its derivatives also showed anti-proliferative activity which was found useful in the treatment of certain cancers." (PMID 26024835, 2015). "The targeting of the PI3K/AKT/MTOR autophagy pathways can overcome cancer cell resistance to chemotherapy and radiotherapy." (PMID 26284195, 2015). "Activation of the PI3K/Akt/mTOR signaling pathway is known to mediate resistance to both chemotherapy and molecularly targeted therapy in various cancers." (PMID 25669984, 2015). "Mechanistically, GOLPH3 regulates cell size, enhances growth-factor-induced mTOR signalling in human cancer cells, and alters the response to rapamycin in vivo." (PMID 26196085, 2015). "The phosphatidylinositol 3-kinase/mammalian target of rapamycin (PI3K/mTOR) signaling pathway is one of the most aberrantly activated survival pathways in cancer, making it an important target for drug development." (PMID 26788526, 2015).
cancer (continued). "Phosphatidylinositol 3-kinase/Akt/mammalian target of rapamycin (PI3K/Akt/mTOR) pathway is a therapy target of cancer." (PMID 26130968, 2015). "A universal convergence mechanism involves over-activating the nutrient-sensing mTOR pathway in both normal and cancer cells." (PMID 26053184, 2015). "The phosphoinositide 3-kinase (PI3K)/mammalian target of rapamycin (mTOR) signaling pathway has been proposed as an interesting therapeutic target in cancer with a pivotal role in cell cycle progression, cell proliferation and angiogenesis." (PMID 26397134, 2015). "Given that overexpression of vascular growth factor receptors are not likely to directly lead to increased angiogenesis in ATCs, mTOR signaling emerges as a key angiogenesis driving pathway in this cancer." (PMID 26680454, 2015). "Regularly, PI3K/Akt/mTOR signaling is activated by growth factors and nutrients; however, this pathway is constitutively active in many cancer types." (PMID 25580621, 2015). "PI3K/Akt/mTOR signaling is involved in several cancer cell metabolic processes, including glycolysis." (PMID 26600164, 2015). "Most impressively, mTOR signalling was blocked by RAD001 in the sunitinib-resistant cancer cells with the same strong potency as was seen in the control assays." (PMID 25444514, 2015). "Among the search results, mTOR and p70S6K1 captured our attention because they were reported to be involved in cisplatin resistance in multiple human cancers." (PMID 26238185, 2015). "On these bases, some anticancer agents, e.g., the mammalian target of rapamycin (mTOR) inhibitors such as rapamycin and derivatives such as everolimus, have been introduced in the field of cancer treatments." (PMID 26423274, 2015). "The use of rapamycin alone in cancer therapy has shown modest success, perhaps due to the re-assembly of mTOR in the mTORC2/Rictor complex, leading to phosphorylation and reactivation of AKT." (PMID 25886314, 2015). "The mammalian target of rapamycin (mTOR), a serine/threonine kinase existing in two functionally distinct complexes (mTORC1 and mTORC2), is commonly up-regulated in various human cancers including NSCLC." (PMID 26517679, 2015). "mTOR has emerged as a critical effector in cell signaling pathways commonly dysregulated in human cancer." (PMID 26536660, 2015). "Previous study has indicated that the muscle wasting in cancer cachexia was strongly related to downregulation of mTOR/p70S6K/4EBP1 pathway." (PMID 26600425, 2015). "Accordingly, the PTEN/PI3K/AKT/mTOR pathway is emerging as a vital target for anti-cancer agents, especially in tumors with mTOR pathway activation." (PMID 26655726, 2015). "mTOR is involved in cancer pathogenesis, and mTOR inhibitors are currently being used as antineoplastic agents." (PMID 26024835, 2015). "Recent work has shown that various cancer cells have elevated mTOR activity due to upregulation of mTOR complex components, e.g., mTOR, RICTOR, RAPTOR, mSIN1, PRAS40, and DEPTOR." (PMID 25906254, 2015). "It has been showed that shikonin or its derivatives inhibit cancer cells via AKT/mTOR and MAPK signaling cascades." (PMID 26472107, 2015). "PI3K/Akt/mTOR pathway plays a major role in cell survival, proliferation, and angiogenesis in human cancer." (PMID 25946033, 2015). "It is now widely accepted that PI3K/Akt/mTOR signalling pathway plays a pivotal role in many human cancers." (PMID 26022660, 2015). "This inhibition of the mTOR pathway translated in blockage of cell growth preferentially in HRAS mutant cancer cell lines." (PMID 26544513, 2015). "The commonly observed activated PI3K/AKT/mTOR pathway contributes to cancer development and maintenance in SCLC." (PMID 25884680, 2015). "Overall, the results of proteomics and western blot confirmed that mTOR pathway was involved in mediating the anti-cancer effect of TMS." (PMID 26542098, 2015).
cancer (continued). "We also identified overexpression of scaffolding proteins that are traditionally involved in the AKT/mTOR pathway including IRS1, RICTOR, and GAB2, which have been implicated as oncogenic contributors in other cancer types." (PMID 25999352, 2015). "Metformin regulates the AMPK/mTOR pathway, possibly through complex I inhibition, interferes with energy metabolism and protein synthesis, and inhibits cancer growth." (PMID 26469226, 2015). "Enriched canonical pathways were also analyzed through IPA, which interestingly revealed p70S6K, mTOR and the signaling of molecular mechanisms of cancer to be among the top canonical pathways triggered by ACSL4 with the lowest p-values." (PMID 26536660, 2015). "An important question for the clinical development of mTOR inhibitors is why ablation of mTOR kinase sensitizes some cancer cells to DNA damage-induced cell death, but has the opposite effect in other cell types." (PMID 25460505, 2015). "Consistent with its central role in controlling cell growth, the mTOR signalling pathway is often hyperactivated in a broad spectrum of human cancers and metabolic diseases." (PMID 26597054, 2015). "The first generation of mTOR inhibitors, including rapamycin and its analogs, block mTORC1 activity, but only show moderate activity in a small subsets of cancers." (PMID 26204252, 2015). "The mTOR pathway is an important target in cancer therapy, as it is involved in the initiation of protein translation necessary for cell growth through the downstream effector 4E-BP1 and ribosomal protein S6 kinase." (PMID 25887473, 2015). "The mechanism by which the drug rapamycin inhibits the mechanistic target of rapamycin (mTOR) is of intense interest because of its likely relevance in cancer biology, aging, and other age-related diseases." (PMID 25652038, 2015). "On the contrary, the mTOR complex is often hyperactivated in cancer and therefore is considered to be an interesting and attractive therapeutic target for anti-cancer therapy." (PMID 25859884, 2015). "Here we explored the role of mTOR (mechanistic target of rapamycin), which serves as a key regulator of cell growth, proliferation and survival, in the metabolic reprograming of cancer cells." (PMID 27551450, 2015). "New data demonstrates that mTOR shows promise as a target for chronic inflammatory pain, neuropathic pain, as well as cancer pain." (PMID 26024835, 2015). "The phosphatidylinositol-3 kinase- (PI3K-) protein kinase- B(Akt-) mammalian target of rapamycin (mTOR) signaling pathway is required for cell growth and plays an important role in progression and metastasis of various cancers." (PMID 25734181, 2015). "The mTOR-mediated metabolism switch in cancer cells provides a novel focus for the dynamic reprogramming of cellular bioenergetics." (PMID 25807077, 2015). "It was shown that Golph3 enlarges cell size, enhances growth-factor-induced mTOR signaling in human cancer cells, and increases the sensitivity to an mTOR inhibitor." (PMID 26156018, 2015). "The AKT/mTOR signaling pathway is a prominent cell-growth promoting pathway that is deregulated in most cancers." (PMID 26287365, 2015). "Phosphorylation of Akt, mTOR and S6 were unaffected by cancer in the non—cachectic mice as measured by western blot." (PMID 25789991, 2015). "Mammalian target of rapamycin (mTOR) signaling is also important for adaptation of cancer cells to hypoxia." (PMID 25879517, 2015). "Modulation of cholesterol homeostasis by NPC2 also affects activation of mammalian target of rapamycin (mTOR), a critical signaling cascade in several types of cancer including HCC." (PMID 26020769, 2015). "The central role of PI3K activation in tumor cell biology has prompted a considerable effort to target PI3K or downstream kinases, such as AKT and mTOR, in cancer." (PMID 26356562, 2015). "Given the importance of mTOR signalling in cancer, a number of inhibitors of this pathway are under study." (PMID 25388238, 2015).
cancer (continued). "For example, metformin, through the inhibition of mTOR, decreases protein synthesis, thus providing a mechanism of action for metformin in the inhibition of cancer-cell proliferation." (PMID 26002551, 2015). "We found that blocking mTOR activity augments shuttling bulk of pyruvate into gluconeogenesis, which results in a ‘futile’ cycling of glucose that leads to halt in cancer cell proliferation and ultimately cell death." (PMID 27551450, 2015). "The most studied effect of metformin is the inhibition of cancer cell proliferation mediated by the inactivation of the mTOR pathway following AMPK activation." (PMID 26291325, 2015). "Our results demonstrate that IL-24 phosphorylation is required for inhibiting the AKT/mTOR signaling pathway and exerting its anti-cancer activities." (PMID 26009991, 2015). "This plethora of active agents makes the PI3K/AKT/mTOR perhaps the most druggable pathway in cancer medicine." (PMID 26056603, 2015). "In this edition, Ed Giessler, a leading basic scientist in experimental and human transplantation, reviews the role of mTOR-inhibitors in cancer." (PMID 27293551, 2015). "The resistance of cancer cells to AKT/MTOR inhibitors is a significant issue in a number of different tumor cells, such as relapsed mantle cell lymphomas." (PMID 26284195, 2015). "Mammalian target of rapamycin (mTOR) is dysregulated in a variety of cancers and considered to be an appealing therapeutic target." (PMID 26176608, 2015). "Inhibition of mTOR by rapamycin or its analogs has been shown to prevent both cancer and aging in various models." (PMID 25895126, 2015). "Recent studies have demonstrated that mTOR also plays a critical role in regulating the motility, invasion and metastasis of cancer cells." (PMID 25996501, 2015). "Since PTEN represses the activation of the PI3K/AKT/mTOR signalling pathway, decreased PTEN expression mediated by miRNAs leads to the activation of the PI3K/AKT/mTOR pathway, which then drives tumour progression and metastasis in many types of cancer." (PMID 26404389, 2015). "The mTOR-pathway is considered a promising candidate for targeted therapies because its relevance and activation has been demonstrated in a variety of cancers and specific inhibitors that have been tested in humans are readily available." (PMID 25993328, 2015). "We also confirmed that mammalian target of rapamycin (mTOR) is one of the targets of miR-99b-5p/100-5p, which is consistent with previous studies in cancer." (PMID 26635599, 2015). "In contrast, mTORC2 is a key regulator of actin cytoskeleton that is correlated with cancer metastasis, and controls the phosphorylation of Akt at Ser-473 through the interaction between rapamycin-insensitive companion of mTOR (rictor) and mTOR." (PMID 26656173, 2015). "While the massive overexpression and overactivity of HER2 is highly unique to these cancer cells, the activities of many of the downstream signaling elements linked with it such as PI3K, Akt, MAPK, and mTor are less unique to cancer cells." (PMID 26516700, 2015). "Studies defining mTORC2 cellular functions and signaling have lagged behind, although the finding that mTORC2 directly phosphorylates AKT adds a new twist in the consideration of the role of mTOR in cancer." (PMID 26536660, 2015). "However, we also need to consider that rATG may increase the risk of de novo cancer, even though recent data indicate this is unlikely and that any risk can be reduced by using mammalian target of rapamycin (mTOR) inhibitors instead of mycophenolic acid combined with low-dose calcineurin inhibitors." (PMID 26457257, 2015). "Knockdown of MTOR is a critical effector of the PIK3-AKT pathway which is dysregulated in many cancers." (PMID 26292663, 2015). "In conclusion, targeting CSCs by inhibiting mTOR signaling is an innovative therapeutic strategy for the treatment of NPC or other cancers." (PMID 26202311, 2015).